CNDP2 (carnosine dipeptidase 2)
Description:
Cytosolic metallodipeptidase with broad substrate specificity that catalyzes the hydrolysis of amide bonds in dipeptides and pseudopeptides. Substrates include L-cysteinylglycine, an intermediate metabolite of the gamma-glutamyl cycle of glutathione metabolism. Can also hydrolyze threonyl-containing dipeptides (By similarity). Upon physiological conditions of amino acids and lactate excess can also catalyze a reverse proteolysis reaction, generating N- [(S)-lactoyl]-L-phenylalanine and possibly other N-lactoyl-amino acids which it can also hydrolyze in vitro. N-[(S)-lactoyl]-L-phenylalanine is an exercise-induced metabolite that influences food intake and systemic energy balance. Carnosine is probably not a physiological substrate and L-homocarnosine is not a substrate for this enzyme. Plays a role in the regulation of cell cycle arrest and apoptosis.
Synonyms: CN2; CPGL; HEL-S-13; PEPA; FLJ10830; HsT2298
Tractability: Small molecule: a structure with a bound ligand is known. PROTAC: ubiquitination databases record sites on it; its protein half-life has been measured.
Target class: Enzyme; Hydrolase
Gene: Protein-coding gene on chromosome 18 (74,494,112 to 74,523,557, forward strand). Ensembl gene ENSG00000133313.
Subcellular location: Cytoplasm, cytosol
Subcellular location (Human Protein Atlas): Cytosol; Nucleoplasm
Pathways (Reactome):
Drug ADME: Paracetamol ADME
Metabolism: Glutathione synthesis and recycling
Gene Ontology:
Molecular function: carboxypeptidase activity; dipeptidase activity; metallodipeptidase activity; protein binding; hydrolase activity; peptidase activity
Biological process: glutathione metabolic process; proteolysis; glutathione catabolic process; nonribosomal peptide biosynthetic process
Cellular component: cytoplasm; cytosol; extracellular exosome; nucleoplasm
Genetic constraint (gnomAD): Loss-of-function variants: 39 observed, 55.6 expected, observed/expected ratio (o/e) 0.7, 90% interval 0.54 to 0.92. The upper end of that interval is the gene's LOEUF score, 0.92, which puts it in group 3 of 6, group 1 being the genes least tolerant of losing a copy. Missense variants: 603 observed, 649.89 expected, observed/expected ratio (o/e) 0.93, 90% interval 0.87 to 0.99. Synonymous variants: 239 observed, 268.96 expected, observed/expected ratio (o/e) 0.89, 90% interval 0.8 to 0.99.
Homologues: Orthologues: chimpanzee CNDP2 (99% identical), guinea pig CNDP2 (92% identical), dog CNDP2 (91% identical), mouse Cndp2 (91% identical), rabbit CNDP2 (90% identical), rat Cndp2 (90% identical), pig CNDP2 (88% identical), tropical clawed frog cndp2 (81% identical), zebrafish cndp2 (78% identical), Drosophila melanogaster Cndp2 (63% identical). Paralogues in human: CNDP1 (53% identical), PM20D1 (19% identical), ACY1 (14% identical).
Diseases named in the same sentence as CNDP2 in open-access papers:
CNDP2 is named in the same sentence as 50 diseases in open-access papers, as found by Europe PMC text mining. Sharing a sentence is not in itself a finding about the gene and the disease. The quoted sentences say what the papers report.
pancreatic cancer (6 papers, 2010 to 2023). "A recent report also demonstrated that the loss of CNDP2 functioned as a tumour suppressor gene in pancreatic cancer and that the loss of CNDP2 suppressed proliferation, induced G0/G1 accumulation, and inhibited the migration ability of a pancreatic cancer cell line." (PMID 24587265, 2014). "A decreased CNDP2 level was observed in pancreatic cancer, hepatocellular carcinoma and gastric cancer." (PMID 30885138, 2019). "Specifically, CNDP2 overexpression in pancreatic cancer lines induced the accumulation of cells in the G0/G1 phase, whereas knockdown of CNDP2 in colon cancer cells blocked the cell cycle progression in the G2/M phase." (PMID 30885138, 2019).
breast carcinoma (5 papers, 2014 to 2025). "Subsequently, we showed, through RT-qPCR and Western blot, that the mRNA and protein expression levels of CNDP2 in ccRCC cell lines 769-P and 786-O were significantly higher than in other cancer cell lines, including liver cancer cell lines LM6 and Huh 7, and breast cancer cell line MCF-7." (PMID 40739140, 2025).
Obesity (5 papers, 2020 to 2025). Accumulation of substantial excess body fat. "Several common SNPs in the CNDP2 gene (rs373836366, rs780772968, rs4891558, and rs7577) have been linked to susceptibility to obesity and renal disease." (PMID 39349903, 2025). "One specific single nucleotide variant (SNV) in CNDP2 has been found associated with obesity risk, whereas other SNVs appear more frequently in athletes, implying a central role in metabolic regulation." (PMID 37064893, 2023). "Cndp1-KO zebra fish have increased carnosine concentrations, and exhibit less body weight gain with high-fat diet than the respective WT fish and a combination of genetic variations in CNDP1 and CNDP2 were associated with obesity risk in Japanese men." (PMID 32664451, 2020). "This warrants further investigation into whether CNDP2‐mediated formation of Lac‐AA and the subsequent decrease in food intake underlies the anti‐obesity effects of these strategies." (PMID 40534243, 2025). "Genome-wide association studies have identified two missense SNPs in CNDP2 (rs373836366 and rs780772968) associated with body mass index and an intron variant (rs4891558) associated with obesity in individuals with high carbohydrate intake and low carotene intake in a Japanese population." (PMID 39349903, 2025). "Relatedly, an in silico study revealed that two anti‐obesity strategies, treatment with trans‐10 and cis‐12 conjugated linoleic acid and caloric restriction, increase Cndp2 expression in adipose tissue in animal models." (PMID 40534243, 2025). "Meanwhile, in a mouse model, the gut epithelium was found to be the main in vivo source of circulating CNDP2 and genetic ablation of Cndp2 in male mice rendered them resistant to metformin’s anti-obesity effects." (PMID 39349903, 2025). "Moreover, they showed that CNDP2 knockout mice, which are resistant to metformin‐inducible increase in Lac‐ Phe, are also resistant to the drug's anti‐obesity effects." (PMID 40534243, 2025). "Interestingly, monocytes are CNDP2+ cells (i.e., macrophages, immune and epithelial cells), where biosynthesis of N-lactoylphenylalanine (Lac-Phe) (from lactate and phenylalanine) occurs against a background of physical activity, which has the function of suppressing appetite and reducing obesity." (PMID 37569635, 2023).
colon carcinoma (4 papers, 2014 to 2024). "An upregulated expression of CNDP2 has been indeed observed in breast carcinoma, and in kidney and colon cancers." (PMID 30885138, 2019). "Second, down-regulation of CNDP2 in colon cancer cells inhibited cell proliferation and influenced cell cycle." (PMID 24885395, 2014). "Our results agree with these studies, and several lines of evidence suggest that down-regulation of CNDP2 inhibits the proliferation of colon cancer." (PMID 24885395, 2014). "Knockdown of CNDP2 can inhibit the proliferation of colon cancer in vitro and retarded carcinogenesis in vivo." (PMID 24885395, 2014). "Knockdown of CNDP2 retarded the growth of tumor cells and colony formation, and inhibited the tumorigenicity of colon cancer cell (RKO) in nude mice." (PMID 24885395, 2014). "Dysregulation of CNDP2 has been indicated in colon cancers, PD, male infertility and obesity." (PMID 38714739, 2024). "Thus, knockdown of CNDP2 inhibited the proliferation of colon cancer cells." (PMID 24885395, 2014). "We found that suppression of CNDP2 blocked cell cycle progression and decreased the expression of cyclin E, cyclin B1 and EGFR in colon cancer cells." (PMID 24885395, 2014).
diabetic nephropathy (4 papers, 2013 to 2025). "For example, carriers of the CC genotype at the rs7577 SNP had lower CNDP2 expression levels and higher risk of diabetic nephropathy." (PMID 40534243, 2025). "While there is no research specifically discussing a link between Lac‐AA and diabetic nephropathy, several single nucleotide polymorphisms (SNPs) in the CNDP2 gene were associated with increased risk." (PMID 40534243, 2025). "We next examined the association of 29 SNPs within the CNDP1/CNDP2 locus with diabetic nephropathy." (PMID 23342076, 2013). "In this study, we examined the association of polymorphisms within the CNDP1/CNDP2 locus, D18S880 and 29 single nucleotide polymorphisms (SNPs), with diabetic nephropathy in Japanese subjects with type 2 diabetes." (PMID 23342076, 2013). "However, notably, diabetic kidney disease markers, such as CCT4 and CNDP2, were more abundant in glomeruli from PTDM patients than in those from T2DM patients." (PMID 37626301, 2023).
gastric cancer (4 papers, 2022 to 2025). A primary or metastatic malignant neoplasm involving the stomach. "In addition, in gastric cancer, CNDP2 may activate the p38 and JNK MAPK pathways, leading to cell apoptosis when highly expressed, or the ERK MAPK pathway, promoting cell proliferation when expressed at a low level." (PMID 38651369, 2024). "PGC expression suppressed the proliferation, anti-apoptosis, migration and invasion of gastric cancer cells possibly by interaction with CCNT1, CNDP2 and CTSB." (PMID 37291517, 2023). "PGC expression suppressed the proliferation and invasion of gastric cancer cells possibly by interacting with CCNT1, CNDP2 and CTSB." (PMID 37291517, 2023).
hepatocellular carcinoma (2 papers, 2014 to 2023). A malignant tumor that arises from hepatocytes. "Tumor suppressor action by CNDP2 has also been observed in hepatocellular carcinoma and in gastric cancer." (PMID 38132151, 2023). "In contrast, the upregulation of CNDP2 has been reported in several tumors such as hepatocellular carcinoma." (PMID 38132151, 2023).
high blood pressure (2 papers, 2014 to 2025). "This list included Angptl7, Hdc, Cndp2, Dna2, Edn3, which were up-regulated in the hypertensive mice and may have a physiological role in the regulation of high blood pressure." (PMID 25259444, 2014). "However, given that the carnosinase activity of CNDP2 has not been elucidated, a potential alternative mechanism through which CNDP2 contributes to regulating hypertension is via Lac-Phe formation, since increased lactate concentrations have been associated with a higher risk of hypertension." (PMID 39349903, 2025).
kidney damage (2 papers, 2013 to 2025). "In mice, induction of acetaminophen overdose, which causes damage by depleting GSH stores, caused kidney damage in CNDP2 mutant mice." (PMID 39349903, 2025). "Measurement of blood urea nitrogen, a marker for kidney damage, was elevated in the CNDP2 mutant mice but not in the control mice." (PMID 39349903, 2025).
laryngeal carcinoma (2 papers, 2014 to 2025). Carcinoma that arises from the laryngeal epithelium. "A study investigated proteomics for diagnostic biomarkers of laryngeal cancer, and four differential proteins (PFN1, NCL, CNDP2, and OGN) with expressional changes were selected to test for differential expressions." (PMID 40051609, 2025). "In consistent with the later researches, our proteomic investigation revealed the overexpression of CNDP2 in the laryngeal carcinoma, and providing the information that this protein might be an accessible biomarker for certain type of cancers." (PMID 24587265, 2014). "Furthermore, we first time show that PFN1, NCL, CNDP2 and OGN may be potential diagnostic and therapeutic targets for laryngeal carcinoma, and demonstrate that PFN1 is involved in the migration of human squamous cells." (PMID 24587265, 2014). "Altogether, our present data first time show that PFN1, NCL, CNDP2 and OGN are novel potential biomarkers for diagnosis and therapeutic targets for laryngeal carcinoma, and PFN1 is involved in the metastasis of laryngeal carcinoma." (PMID 24587265, 2014). "Taken together, in this study, the use of 2D LC-MS/MS identified 281 significantly differentially expressed proteins in human laryngeal carcinoma, and four differential proteins (PFN1, NCL, CNDP2 and OGN) with expressional changes were selectively verified." (PMID 24587265, 2014). "Next, semiquantitative RT-PCR was performed to detect the mRNA levels of PFN1, NCL, CNDP2 and OGN in 8 cases of paired laryngeal carcinoma tissues." (PMID 24587265, 2014). "And the results revealed that the expression of PFN1, NCL, and CNDP2 was elevated and that of OGN was reduced in laryngeal carcinoma tissue compared with the adjacent normal tissue." (PMID 24587265, 2014). "Thus, the expression of PFN1, NCL, CNDP2 and OGN were further investigated employing a large collection of human laryngeal carcinoma tissues." (PMID 24587265, 2014).
ovarian carcinoma (2 papers, 2022 to 2025). A malignant neoplasm originating from the surface ovarian epithelium. "Furthermore, the expression of SERPINH1 was high in patients in gene cluster C. Previous studies have shown that CNDP2 is pro-oncogene, involved in cell proliferation and metastasis in ovarian cancer via the PI3K/AKT pathway." (PMID 36700224, 2022). "CNDP2 has not previously been reported within HPV+OPSCC but is highly expressed within ovarian cancer and indicates an overall poor prognosis." (PMID 40014866, 2025).
renal carcinoma (2 papers, 2011 to 2025). A carcinoma arising from the epithelium of the renal parenchyma or the renal pelvis. "One interesting gene is CNDP2, known to be overexpressed in renal cancer, but only in grade 1 and 2 cancers, with levels in grade 3 and 4 cancers being the same as those of normal tissues." (PMID 21955394, 2011). "Renca is a murine renal cancer cell line that highly expresses CNDP2." (PMID 40739140, 2025).
atherosclerosis (1 paper, 2024). A disease characterized by the build-up of fatty material and calcium deposition in the arterial wall resulting in partial or complete occlusion of the arterial lumen. "While, in atherosclerosis, interactions were found between up-DEGs including B2M (combined score: 0.978), CNDP2 (combined score: 0.969) interacted with cysteine." (PMID 38415056, 2024).
clear cell renal cell carcinoma (1 paper, 2025). "Further bioinformatics analysis revealed that clear cell renal cell carcinoma (ccRCC) has the highest CNDP2 expression level among the 33 types of cancer tissues." (PMID 40739140, 2025).
heart failure (1 paper, 2025). Inability of the heart to pump blood at an adequate rate to meet tissue metabolic requirements. "This includes exploring potential associations between CNDP2 and specific cardiovascular conditions, such as heart failure and myocardial infarction." (PMID 39349903, 2025).
nephritis (1 paper, 2014). Inflammation of renal tissue. "Further genes were annotated with nephritis (Cndp2, Dnase1 and Scd1)." (PMID 25409434, 2014).
Parkinson disease (1 paper, 2025). A progressive degenerative disorder of the central nervous system characterized by loss of dopamine producing neurons in the substantia nigra and the presence of Lewy bodies in the substantia nigra and locus coeruleus. "The exact mechanisms of how CNDP2 drives (or inhibits) cancer and Parkinson’s disease development have yet to be established." (PMID 39349903, 2025). "Meanwhile, CNDP2 is hypothesised to be involved in Parkinson’s disease through oxidative stress, protein aggregation, or inflammation." (PMID 39349903, 2025). "Altered protein expression of CNDP2 has been observed in various cancers and Parkinson’s disease." (PMID 39349903, 2025).
prediabetes (1 paper, 2025). "Compared to the control group, we detected 130 DMCs that were shared between the prediabetes and T2D groups, with LCLAT1, HLA-C, NINJ2, ZNF714, CNDP2, and HOOK2 among the top differentially methylated genes." (PMID 41373473, 2025).
prostate carcinoma (1 paper, 2022). A carcinoma that arises from epithelial cells of the prostate gland. "According to our in vitro experiments, we found that CNDP2 and SERPINH1 promote tumor invasion and cell proliferation and reduce cell apoptosis in prostate cancer." (PMID 36700224, 2022). "Knockdown of CNDP2 and SERPINH1 expression inhibited the proliferation of prostate cancer cell lines." (PMID 36700224, 2022). "The qPCR results revealed that the expression of CNDP2 was high in four PC cell lines (LNCap, PC-3, C4-2, and 22RV-1), and the expression of SERPINH1 was high in immortalized prostate cell lines like RWPE-1 compared with four prostate cancer cell lines." (PMID 36700224, 2022).
sarcopenia (1 paper, 2024). Progressive decline in muscle mass due to aging which results in decreased functional capacity of muscles. "However, the role of CNDP2 in conditions like frailty, sarcopenia, and vascular aging requires further research in experimental and clinical settings." (PMID 38415056, 2024).
Sepsis (1 paper, 2024). Sepsis is defined as life-threatening organ dysfunction caused by a dysregulated host response to infection. "Experimental sepsis studies in CNDP2 KO mice could provide mechanistic insights into the function of lac-AAs." (PMID 38446263, 2024).